ZNF559 (zinc finger protein 559)
Description:
May be involved in transcriptional regulation.
Synonyms: MGC13105; NBLA00121
Tractability: PROTAC: ubiquitination databases record sites on it.
Gene: Protein-coding gene on chromosome 19 (9,323,717 to 9,351,162, forward strand). Ensembl gene ENSG00000188321.
Subcellular location: Nucleus
Subcellular location (Human Protein Atlas): Nucleoplasm; Cytosol
Pathways (Reactome):
Gene expression (Transcription): Generic Transcription Pathway
Gene Ontology:
Molecular function: protein binding; DNA-binding transcription factor activity, RNA polymerase II-specific; RNA polymerase II transcription regulatory region sequence-specific DNA binding
Biological process: regulation of transcription by RNA polymerase II; regulation of DNA-templated transcription
Cellular component: nucleoplasm; nucleus
Genetic constraint (gnomAD): Loss-of-function variants: 17 observed, 15.09 expected, observed/expected ratio (o/e) 1.13, 90% interval 0.77 to 1.67. The upper end of that interval is the gene's LOEUF score, 1.67, which puts it in group 6 of 6, group 1 being the genes least tolerant of losing a copy. Missense variants: 740 observed, 662.76 expected, observed/expected ratio (o/e) 1.12, 90% interval 1.05 to 1.19. Synonymous variants: 244 observed, 222.99 expected, observed/expected ratio (o/e) 1.09, 90% interval 0.99 to 1.22.
Homologues: Orthologues: macaque ZNF559 (95% identical), chimpanzee ZNF559 (86% identical), Drosophila melanogaster CG3281 (24% identical), Drosophila melanogaster CG2712 (20% identical), Drosophila melanogaster Phs (19% identical). Paralogues in human: ZNF560 (42% identical), ZNF266 (41% identical), ZNF177 (40% identical), ZNF20 (38% identical), ZNF555 (38% identical), ZNF778 (38% identical), ZNF674 (37% identical), ZNF248 (36% identical), ZNF69 (36% identical), ZNF805 (36% identical), ZFP90 (35% identical), ZNF404 (35% identical), and 50 more.
Diseases named in the same sentence as ZNF559 in open-access papers:
ZNF559 is named in the same sentence as 1 disease in open-access papers, as found by Europe PMC text mining. Sharing a sentence is not in itself a finding about the gene and the disease. The quoted sentences say what the papers report.
psoriasis (1 paper, 2015). An autoimmune condition characterized by red, well-delineated plaques with silvery scales that are usually on the extensor surfaces and scalp. "Several TFs/uDBPs additionally showed altered expression in blood from psoriasis patients (increased: JUNB, STAT3, DTL, CAT; decreased: CUX2, ZNF559, AVEN, RUVBL1, RAN)." (PMID 25883770, 2015).